BCL3 (BCL3 transcription coactivator)
Diseases named in the same sentence as BCL3 in open-access papers (continued):
Sharing a sentence is not in itself a finding about the gene and the disease.
tumor (continued). "The tumor cells were negative for the BCL3 gene rearrangement, indicating that the BCL3 gene is not the novel gene fusion partner of TFE3 in the case herein presented." (PMID 19450277, 2009). "Interphase FISH analysis performed on cultured and uncultured tumor cells using a dual-color break-apart DNA probe within the BCL3 gene on 19q13.3 was negative for the BCL3 gene rearrangement." (PMID 19450277, 2009). "Clinically, BCL-3 expression is negatively correlated with survival in CRC patients, where strong nuclear staining of BCL-3 observed in tissue microarrays was associated with reduced patient survival and additionally shown to be independent of tumour stage." (PMID 35468497, 2022). "Some genetic testing methods may be feasible for determining whether tumor tissues highly express RUNX1 and the corresponding downstream genes (BCL3, MGP, and MXI1), consistent with our experimentally validated results: in positive cases, targeting RUNX1 may be a suitable optional treatment." (PMID 31754093, 2019). "RORγ1 regulated tumor-promoting “emergency” granulo-monocytopoiesis by suppressing negative (Socs3 and Bcl3) and promoting positive (C/EBPb) regulators of granulopoiesis and RORγ1 promoted expansion of tumor-promoting MDSCs and TAM in fibrocarcinoma mice models." (PMID 29904382, 2018). "The importance of Bcl3 in maintaining tumour cell survival in the absence of exogenous stress inducers, however, remains unclear, with transgenic ErbB2 and triple-negative mouse models showing little effect on primary tumour growth following Bcl3 inhibition." (PMID 38255248, 2024). "Along with these findings, we demonstrated that BCL3 expression is able to distinguish healthy esophagus from non-tumor tissue adjacent to ESCC with high accuracy, sensitivity, and specificity and could help to identify the patches of premalignant esophageal cells." (PMID 34422669, 2021).
infection (25 papers, 2007 to 2025). The state of being infected such as from the introduction of a foreign agent such as serum, vaccine, antigenic substance or organism. "Consistent with this, compared to wildtype controls, splenic Xcr1+ Bcl3-deficient cDC1 cells were defective in presenting Ova antigen to OT-I cells both for Ova257-264 peptide and after infection with Ovalbumin-expressing T. gondii." (PMID 36318581, 2022). "We also showed that infection with Toxoplasma gondii is uniformly fatal in mice globally deficient in Bcl3 (Bcl3−/−), which correlated with a defective Th1-type response." (PMID 36318581, 2022). "icDC2 levels were also increased by infection in spleen and lung; however, the peak levels were similar for both wild type and total Bcl3-deficient mice." (PMID 36318581, 2022). "Bcl-3-deficient mice showed first disease symptoms around day 128 p.i. and terminal disease by day 143 ± 5.8 after infection." (PMID 17573907, 2007). "To analyse various NF-κB signalling pathways we used NF-κB1-, NF-κB2- and Bcl-3-deficient mice and animals with p65 depletion in the CNS for infection with PrPSc." (PMID 17573907, 2007). "Bcl3flx/flxZbtb46 cre mice and complete Bcl3-/- mice were both uniformly susceptible to fatal T. gondii infection, whereas almost all wildtype mice survived until pre-scheduled euthanasia at day 40 post infection (PI)." (PMID 36318581, 2022). "Together, these changes suggest a reduced capacity for antigen presentation and cross-presentation in Bcl3-deficient cDC1 cells compared to wildtype in the context of infection even though the expression level of MHC class I genes was intact or slightly increased in the Bcl3-deficient cells." (PMID 36318581, 2022). "As early as 7 days after infection, dramatic but transient increases in both the frequency and number of icDC1 occurred in both spleen and lung in wild type mice, however this increase was markedly reduced in infected total Bcl3-deficient mice." (PMID 36318581, 2022). "Animals with a deficiency in Bcl-3 present with defects in the microarchitecture of their secondary lymphoid organs and disrupted adaptive immune responses, resulting in increased susceptibility to infection." (PMID 27023613, 2016). "An increase of Bcl-xL-positive cells in RML6-infected C57Bl/6 mice compared with uninfected animals was found at 11 weeks after infection, while a reduced number of Bcl-xL-expressing cells was found in the brain of NF-κB2- and Bcl-3-deficient mice compared with C57Bl/6 mice at the same time point." (PMID 17573907, 2007). "The upregulation of BCL-3 was observed early at h 3 post-infection while the most remarkable change in A20 was detected at h 48 for both subtypes of SIV." (PMID 40565228, 2025). "In serum, we found that both IFN-γ and IL-12 levels were markedly increased at both 7 and 21 days after infection in both wildtype and Bcl3flx/flxZbtb46 cre- (Bcl3 sufficient) mice compared to levels in uninfected control mice." (PMID 36318581, 2022). "Prior to infection, the content of CD11c+MHC II+ cells, which include dendritic cells, was similar for wildtype and both complete and conditional Bcl3-deficient strains in both organs." (PMID 36318581, 2022). "Within the CD8+ EM subset, both vaccination and infection resulted in the upregulation of BCL3, which is essential for maximum IFN-γ secretion following secondary antigen stimulation." (PMID 34935643, 2021). "It is possible that the protegrin treatments assisted in combating infection, and thus Bcl-3 expression remained similar to that in the unchallenged mice." (PMID 34502403, 2021). "Three days post-infection, we analyzed the binding of the p65 and p50 subunits of NF-κB, c-Jun subunit of AP-1, c-Fos subunit of AP-1, and the Bcl-3 and H3 proteins to HIV-1 DNA in the R-U5 region (total viral DNA)." (PMID 27167871, 2016).
infection (continued). "Thus, the activation of p52/Bcl-3 complexes in MDMs in response to HCMV-DB infection resulted in the activation of the pro-oncogenic Bcl3 factor parallel to an M2 phenotype." (PMID 36366560, 2022). "We also identified by scRNAseq, a unique Bcl3-dependent hybrid subpopulation of Zbtb46+ DCs co-expressing the monocyte/macrophage transcription factor Lysozyme M. This subpopulation exhibited Bcl3-dependent expansion after infection." (PMID 36318581, 2022). "cDC1 cells from both uninfected wildtype and uninfected Bcl3flx/flxZbtb46 cre mice expressed similar levels of genes related to antigen presentation except those related to MHC class Ib genes (H2-M3, Mr1, Cd1d), which seemed to be affected by Bcl3 deficiency even in the absence of infection." (PMID 36318581, 2022). "Pathways involved in chemokine receptor signaling were also significantly enriched, highlighting the recruitment of immune cells to the site of infection (NFKBIA, NFKBIB, NFKBIE, NFKBIZ, TNFAIP3, REL, BCL3)." (PMID 40634947, 2025). "In line with these previous studies, we observed here that the infection of PBE cells with either H1N1 or H3N2 SIV increased A20, BCL-3, and MKP-1 expressions." (PMID 40565228, 2025). "Treatment with a synthetic peptide, SPIKENET (SPK), which inhibits spike protein binding, reduced NGAL mRNA in acute infection, and decreased TGF-β1, BCL3 mRNA, EGFR, HIF1-α, and TLR-2 protein levels long-term post-MHV-1 infection." (PMID 37626956, 2023). "When the negative regulators of the TLR signaling pathway were investigated after infection of PIE cells with rotavirus, it was observed that both FFIG35 and FFIG58 were capable of reducing the expressions of A20, Bcl-3, Tollip and IRAK-M." (PMID 34163470, 2021). "In the present study, we show that mice lacking the NF-κB regulator Bcl3 in cells expressing Zbtb46, a selective marker of cDCs, succumb 3–5 weeks after i.p. infection with T. gondii." (PMID 36318581, 2022). "However, in response to infection, male mice exhibited higher expression levels of CXCL2 (KO, 1A3, and 6A2), SAMHD1 (1A0, 1A3), RSAD2, STAT1, and STAT3 (1A0), MYD88 and PSMB8 (1A3), BCL3, BCL10, CCRL2, IFITM2, RTP4, and ZFP36L1 (6A2), compared to females." (PMID 32670284, 2020). "Finally, several pro-apoptotic genes, including Bcl3, Bcl10, Malt1 and Dedd2, were up-regulated in response to muriform cells infection whereas Bcl2l12, coding to anti-apoptotic factor, was down-regulated, suggesting that infection of macrophages with muriform cells could induce apoptosis." (PMID 28355277, 2017). "Another striking feature of SLOs in Bcl3−/− mice is the virtual absence of GCs under steady-state conditions, and GCs are poorly induced by infection or immunization with experimental model Ags." (PMID 27023613, 2016). "This suggests that once a CD8+ T cell had chosen its path earlier during the infection, under the influence of Bcl-3, thereafter Bcl-3 no longer controlled gene expression, at least not the genes that could be detected in our scRNA-seq analysis." (PMID 33508001, 2021). "To investigate whether NF-κB is involved in prion pathogenesis in vivo, we used mice lacking either p65 or p50, compounds of the classical NF-κB pathway, or mice lacking p52 or Bcl-3 for infection with PrPSc." (PMID 17573907, 2007). "Interestingly, MKN-28 cells infected with ΔhtrA at both 2-h and 6-h time points exhibited increased TNF expression implying that HtrA may be involved in TNF signaling, a view that was supported by the observed deregulation of ZFP36, BCL3 and TNF during infection with the ΔhtrA mutant." (PMID 37193047, 2022). "This suggests that after infection by NL4-3 WT under standard conditions, p50/p65 is present on iDNA rather than on uDNA, whereas Bcl-3 and AP-1 are mainly bound to uDNA." (PMID 27167871, 2016).
adenocarcinoma (3 papers, 2020 to 2024). A common cancer characterized by the presence of malignant glandular cells. "Interestingly, similar to involuting glands, a subset of adenocarcinomas and anaplastic tumors in bcl-3−/− mice expressed elevated levels of Puma compared to WT tumors." (PMID 35681213, 2022). "Tumors in WT mice were predominately adenocarcinomas with NF-κB activation, while bcl-3−/− lesions were largely squamous lacking NF-κB and with low Bcl-2 expression." (PMID 35681213, 2022). "We observed a significant increase in CNA in FGFR3, BCL3, and IDH2 in CCNE1-amplified versus nonamplified EG adenocarcinoma." (PMID 38717153, 2024).
immune diseases (2 papers, 2016 to 2023). "Since Bcl-3 influences the function of adaptive immune cells, it is perhaps unsurprising that aberrant Bcl-3 expression has been associated with a range of immune dysfunctions." (PMID 27023613, 2016). "Overall, we provide novel insights into the regulatory role of Bcl-3 in T-cell energy metabolism for the prevention and treatment of immune diseases." (PMID 37794349, 2023). "Our results may provide novel insights into the regulatory role of Bcl-3 in T-cell energy metabolism for the prevention and treatment strategies of immune diseases." (PMID 37794349, 2023).
kidney disease (2 papers, 2019 to 2023). "BCL3 serves as an important regulator of nuclear factor kappa-light-chain-enhancer of activated B cells (NF-kB) and has been implicated in renal disease, exhibiting increased expression." (PMID 37626956, 2023).
neurological diseases (2 papers, 2017 to 2019). "Among these genes, Ch25h, Trpa1, Cdkn1a, Ly6g6e, Six3, and Opalin are potentially associated with neurological diseases; Lcn2, Serpina3f, Lao1, Trim29, bcl3, and Gkn3 are associated with inflammatory response." (PMID 30804943, 2019).
vascular disorder (1 paper, 2017). A general term used to describe any disease affecting blood vessels]. "Complexes such as Bcl3/NF-kappaB2 complex (governed by BCL3 and NFKB2), vacuolar lumen (governed by CLN5), IPAF inflammasome complex (CASP1, CASP4, NLRC4) help to understand the involvement of inflammation and vascular disorder in AD." (PMID 28199395, 2017).
BCL3 also shares sentences with these, for which no sentence is quoted: asthma (3 papers); benign tumors (2); breast (2); chronic kidney disease (2); coronary artery disease (2); depression (2); diffuse large B-cell lymphoma (2); follicular lymphoma (2); lung adenocarcinoma (2); adult T cell leukemia (1); Arthritis (1); basal cell carcinoma (1); behavioral disorders (1); bone metastasis (1); Burkitt lymphoma (1); cholesteatoma (1); dwarfism (1); dyslipidemia (1); endometrial carcinoma (1); epilepsy (1); familial Alzheimer disease (1); familial cylindromatosis (1); gastric cancer (1); gastric tumor (1); genetic disease (1); gorlin syndrome (1); heart failure (1); Hepatic steatosis (1); immunodeficiency disease (1); inflammation (1).
A further 33 diseases each share a sentence with BCL3 in 1 paper.